MAILR (macrophage interferon regulatory lncRNA)
Synonyms: MAIL1; H22954; formerly AZIN1-AS1
Gene: Long non-coding RNA gene on chromosome 8 (102,864,029 to 103,002,424, forward strand). Ensembl gene ENSG00000253320.
Diseases named in the same sentence as MAILR in open-access papers:
MAILR is named in the same sentence as 1 disease in open-access papers, as found by Europe PMC text mining. Sharing a sentence is not in itself a finding about the gene and the disease.
MAILR shares sentences with these, for which no sentence is quoted: COVID-19 (1 paper).